MIR181C (microRNA 181c)
Synonyms: hsa-mir-181c; MIRN181C; mir-181c
Gene: MicroRNA gene on chromosome 19 (13,874,699 to 13,874,808, forward strand). Ensembl gene ENSG00000207613.
Pathways (Reactome):
Signal Transduction: Pre-NOTCH Transcription and Translation
Gene Ontology:
Biological process: miRNA-mediated post-transcriptional gene silencing
Cellular component: RISC complex
Homologues: Orthologues: chimpanzee ptr-mir-181c (100% identical), macaque mml-mir-181c (95% identical), rat Mir181c (85% identical), dog MIR181C (77% identical), pig MIR181C (77% identical), mouse Mir181c (72% identical), guinea pig MIR181C (70% identical). Paralogues in human: MIR181A1 (58% identical), MIR181A2 (57% identical), MIR181B1 (44% identical), MIR181B2 (38% identical).
Diseases named in the same sentence as MIR181C in open-access papers:
MIR181C is named in the same sentence as 3 diseases in open-access papers, as found by Europe PMC text mining. Sharing a sentence is not in itself a finding about the gene and the disease. The quoted sentences say what the papers report.
kidney cancer (1 paper, 2009). Primary or metastatic malignant neoplasm involving the kidney. "In particular, CUL3, over expressed in kidney and prostate cancers, is a target of several dysregulated MIRs: MIR22, MIR23A, MIR23B, MIR218-1, MIR218-2, and MIR301, which are down regulated in kidney cancers, and of MIR22, MIR23A, MIR181A, and MIR181C, which are down regulated in prostate cancers." (PMID 19402918, 2009).
MIR181C also shares sentences with these, for which no sentence is quoted: pancreatic adenocarcinoma (1 paper); prostate carcinoma (1).